GPX7 (glutathione peroxidase 7)
Diseases named in the same sentence as GPX7 in open-access papers (continued):
Sharing a sentence is not in itself a finding about the gene and the disease.
neuropathy (1 paper, 2024). A disorder affecting the nervous system that manifests with pain, tingling, numbness, and/or muscle weakness. "Specific genes increased in patients withoutlinezolid-associated neuropathy included ATG4C, BAX, and IGF1, while patients onlinezolid who suffered from neuropathy had an increase in AURKB, CASP3, CASP8, CDK1,CDKN1B, CEBPB, NADSYN1, NRF1, GPX7, and SBSN." (PMID 38939039, 2024).
non-alcoholic fatty liver disease (1 paper, 2021). "It is proved that the higher expressions of glutathione peroxidase-7 inhibited non-alcoholic fatty liver disease via decreasing production of ROS." (PMID 33435504, 2021).
osteoporosis (1 paper, 2021). A condition of reduced bone mass, with decreased cortical thickness and a decrease in the number and size of the trabeculae of cancellous bone (but normal chemical composition), resulting in increased fracture incidence. "Since the imbalance between osteogenic and adipogenic differentiation of bone marrow mesenchymal stem cell (BMSC) leads to severe bone diseases such as osteoporosis, it is critical to investigate the potential protective role of Gpx7 in osteogenesis." (PMID 34626080, 2021).
skin ulcerations (1 paper, 2022). "The increased ROS levels, paralleled by decreased expression of ROS scavengers like GPX7, likely further contribute to the propensity for skin ulcerations, for instance by inducing serine proteases and MMPs, which can negatively affect ECM and wound repair." (PMID 34847081, 2022).
tendinopathy (1 paper, 2023). "PRDX4 and GPX7 were upregulated in tendinopathy samples; however, because their expression levels were quite low, the effect of this upregulation was not assumed to be significant." (PMID 37021050, 2023).
viral infection (1 paper, 2023). "GPx-7 has also been related to metabolic diseases, neurodegeneration, viral infection, and cardiovascular diseases." (PMID 37761814, 2023).
Werner syndrome (1 paper, 2018). "We observed that the expression levels of Nrf2 and GPx7 decreased in both replicative senescent HMSCs and premature senescent HMSCs (Werner syndrome‐specific: WRN‐deficient)." (PMID 29659168, 2018).
tumor (21 papers, 2010 to 2025). "Here, we found that GPX7 was negatively associated with the tumor purity in LGG (ρ = − 0.486; p = 8.63e−30) but positively correlated to it in GBM (ρ = 0.311; p = 2.02e−04)." (PMID 35440701, 2022). "A mutation in GPx7 could possibly prove detrimental to its function regarding the cellular processes of apoptosis and tumor suppression." (PMID 39796732, 2024). "Our data report a strong correlation between GPX7 expression with the M2 macrophages markers (CD163, VSIG4, MS4A4A), implying a potential role for GPX7 in the polarization of tumor-associated macrophages (TAM) in LGG169." (PMID 35440701, 2022). "In light of these data, it is reasonable to suggest that inflammation and ROS generation are interconnected in a feedforward loop during tumor development, triggering GPX7 expression." (PMID 35440701, 2022). "Previous studies have demonstrated that GPX1 to GPX7 play important roles in the carcinogenesis of tumor." (PMID 35712475, 2022). "We also found that GPX7 strongly correlates with immune cell infiltration and diverse immune cell markers, suggesting its role in tumor-specific immune response and in regulating the migration of immune cell types to the tumor microenvironment." (PMID 35440701, 2022). "The results indicated that the GPX7 expression was related to multiple tumor-related pathways, including the cell cycle pathway, ECM pathway, focal adhesion pathway, and toll-like receptor pathway." (PMID 33750478, 2021). "A tumor xenograft model was established by subcutaneously inoculating LN229 cells infected with lentiv-NC or lentiv-GPX7, respectively." (PMID 35127512, 2021). "In TCGA, GSE16011 and Rembrandt, GPX7 expression was upregulated in tumor with grade IV compared with those with lower grades." (PMID 35127512, 2021). "GSEA revealed that some tumor-related signaling pathways and immunity-related activities are enriched in the GPX7 high expression group." (PMID 35127512, 2021). "We have found that MKN45 cells grow well in 3D organotypic cultures; we therefore used this cell line for testing the effects of GPX7 reconstitution on tumor growth in 3D model." (PMID 28903346, 2017). "Conversely, genes that were under-expressed in tumor versus normal brain in animals fed a SD (Cyba, Noxo1, Prdx4 and Gpx7) were over-expressed in tumor from animals fed a KD." (PMID 20831808, 2010). "GPX7 has been confirmed to inhibit tumorigenesis, and may function as a tumor suppressor in multiple tumors." (PMID 37293295, 2023). "Together, these findings strongly suggest that GPX7 may be involved in tumor inflammatory response, which might be responsible for modulating the immune molecules and TILs migration, impacting patient outcomes, especially those with LGG." (PMID 35440701, 2022). "In our study, we firstly found up-regulation of GPX7 in a pan-cancer analysis, suggesting that GPX7 might function as an extensive tumor-promoter." (PMID 35440701, 2022). "We detected GPX7 promoter hypermethylation (> 10% DNA methylation level) in 55.6% (25/45) of tumor tissue samples (range: 11%–65%) while only 13.3% (6/45) of normal gastric tissues showed > 10% methylation levels (range: 11%–24%) (Fisher exact test, p < 0.0001)." (PMID 28903346, 2017). "Indeed, tumor cell growth was significantly suppressed by reconstitution of GPX7 expression in our 2D colony formation assay and 3D organotypic cell culture model." (PMID 28903346, 2017). "GPX7 (glutathione peroxidase 7) may function as tumor suppressor." (PMID 27206673, 2016). "Non-tumor HepaRG cells exhibited a much higher expression of GPX8 and a much lower expression of GPx7." (PMID 37189460, 2023). "Significantly, the results of IHC staining also indicated the distinct difference of prognostic genes including SEPHS2, GPX7, and PFKFB3 between tumor and adjacent normal tissues." (PMID 37293295, 2023).
tumor (continued). "Seven genes of the prognostic model (COPA, GPX7, ITGB5, MATN3, MCM7, MMP1, and SPP1) have been validated to be related to tumor progression, whereas the remaining three genes, BNDF, GADD45B, and LOX, need to be further analyzed." (PMID 35699863, 2022). "The group subjected to the combination of GPX7 knockdown and erastin treatment showed a significant tumor growth inhibition, wheras the mice subjected to GPX7 knockdown alone exhibited no tumor growth suppression." (PMID 35127512, 2021). "On the contrary, the MKN45 cells failed to grow and form tumor layers following reconstitution of GPX7 (Ad-GPX7)." (PMID 28903346, 2017). "In contrast to Gpx7 and Prdx4, cytoglobin (Cygb) - which also protects cells against oxidative stress - was more highly expressed in tumor vs. non-tumor tissue in animals fed a SD, as well as in normal brain when mice were fed a KD." (PMID 20831808, 2010). "However, GPx7 is thought to act as a tumor suppressor in non-malignant esophageal cells." (PMID 39796732, 2024).
cancer (13 papers, 2016 to 2024). A tumor composed of atypical neoplastic, often pleomorphic cells that invade other tissues. "In our analysis, we observed a range of folding energy changes caused by missense mutations in GPx7-associated cancers." (PMID 39796732, 2024). "The abnormal expression of GPX7 is related to pathological conditions, for example, the deletion of GPX7 increases the differentiation of preadipocytes and the risk of cancer." (PMID 35699863, 2022). "Furthermore, the aberrant function of GPx7 has been linked to ROS accumulations, highly elevated cancer incidences, auto-immune disorders, and obesity." (PMID 39796732, 2024). "Additionally, it is crucial to recognize that mutations in other genes might also play a role in the development of cancers linked to GPx7 and GPx8, underscoring the complexity of the genetic factors involved." (PMID 39796732, 2024). "In a pan-cancer analysis of multiple cancer, GPx7 was overexpressed and posed as a potential biomarker for glioma prognosis." (PMID 39796732, 2024). "The studies of the functions of GPx5, GPx6, GPx7, and GPx8 in cancer development are limited in comparison with those of Gpx1–Gpx4." (PMID 39125992, 2024). "Knockdown of Gpx3 and Gpx7 in cancer cells was sufficient to increase the accumulation of ROS after treatment with FIRINOX, and increased the susceptibility of the cancer cells to FIRINOX to a similar extent as 3-IAA and FIRINOX." (PMID 36813961, 2023). "On one hand, the increased expression of GPX7 and LOX was associated with the chemotherapy resistance of cancer cells to Fluphenazine, arsenic trioxide, nellarabine, erlotinib, and lenvatinib." (PMID 35699863, 2022). "To this end, we explored the expression patterns of GPX7 from a pan-cancer perspective, using microarray data through the differential analysis tool of the Oncomine database." (PMID 35440701, 2022). "The results showed the expression of most of the hub genes was positively related to the IC50 of cancer therapy drugs while the expression of GPX7 was the opposite." (PMID 35769483, 2022). "Glutathione peroxidase 7 (GPX7) is a member of GPX family which is downregulated in some cancer types." (PMID 28903346, 2017). "To confirm that GPX7 is silenced by an epigenetic molecular mechanism, we treated AGS and SNU1 cancer cells (GPX7 is silenced in both cell lines) with 5-Aza (a DNA methyltransferase) alone or in combination with TSA (a histone deacetylase inhibitor)." (PMID 28903346, 2017). "Using pyrosequencing technology, we quantitatively analyzed GPX7 promoter DNA methylation in all cancer cell lines." (PMID 28903346, 2017). "For example, the interaction between P4HB and GPX7/GPX8 might impact cancer cell responses to oxidative stress." (PMID 38029391, 2023). "Furthermore, the malfunction of GPx-7 contributes to tumorigenesis and the progression of diverse types of carcinomas in humans." (PMID 37761814, 2023). "However, to the best of our knowledge, few studies have investigated the GPX7 expression and its impact on most cancers." (PMID 35440701, 2022). "The dysregulation of GPX7 may lead to some diseases, including cancer." (PMID 39125992, 2024). "Interestingly, the survival curves showed that low expression of GPX7 along with low immune infiltration of CD4+ T cells, neutrophil, myeloid dendritic cell (mDCS) and cancer associated fibroblast (CAF) have better prognosis than the high TIL- and GPX7-expressing group in LGG." (PMID 35440701, 2022). "The biology of GPX7 and its effects in multiple cell types and pathologic contexts are only beginning to be dissected, and further mechanistic studies investigating GPX7 roles in cancer and immunity might reveal more complex mechanisms." (PMID 35440701, 2022). "Given P4HB's role in protein folding and GPX7/GPX8's function in scavenging ROS, their interaction could influence the redox environment crucial for cancer cell survival and proliferation." (PMID 38029391, 2023).
cancer (continued). "Further, we observed that LIUS has the tendency to induce antioxidant effects in non-cancer cells by attenuating the gene expression of NOS2 and NOS3, which promote ROS generation, while promoting the expression of antioxidant genes GPX3 and GPX7." (PMID 31355136, 2019). "Therefore, the cumulative negative impact of GPX7 on cancer cells includes not only reduction of their proliferative capacity, but also induction of cell death." (PMID 28903346, 2017).
GPX7 also shares sentences with these, for which no sentence is quoted: glioblastoma (3 papers); colon carcinoma (2); leukemia (2); liver cancer (2); lymphoma (2); melanoma (2); myeloma (2); oligoastrocytoma (2); oligodendroglioma (2); adenocarcinoma (1); amyotrophic lateral sclerosis (1); anaplastic oligodendroglioma (1); cardiovascular diseases (1); Cerebral ischemia (1); gastroesophageal reflux disease (1); glomerulonephritis (1); heart failure (1); hepatoblastoma (1); metabolic disease (1); mixed glioma (1); oral cancer (1); parasitic infections (1); peripheral neuropathy (1); prostate carcinoma (1); pulmonary hypertension (1); Renal cyst (1); Splenomegaly (1); Stroke (1); type 2 diabetes mellitus (1); ulcerative colitis (1).